INS (insulin)
Diseases named in the same sentence as INS in open-access papers (continued):
Sharing a sentence is not in itself a finding about the gene and the disease.
diabetes (continued). "While 32% of diabetes patients were on diet regimen only, 58% used oral hypoglycaemic agents and diet only, and another 10% took insulin." (PMID 20553622, 2010). "Insulin and SS secreted by islet cell are related to some current diseases with high incidence, for example, diabetes." (PMID 21151458, 2010). "In STZ-induced diabetic rats, diabetes develops as a result of irreversible pancreatic β-cell destruction leading to degranulation and reduced insulin secretion." (PMID 20559501, 2010). "Increased blood glucose level observed during diabetes is similar with previous reports as a result of the marked destruction of insulin secreting pancreatic β-cells by streptozotocin." (PMID 20868513, 2010). "During the ICU stay, more patients with insulin-treated diabetes required renal replacement therapy (hemodialysis or hemofiltration) than other patients." (PMID 20132545, 2010). "A computational model has been used to determine the steady-state basal plasma glucose and insulin concentrations determined by their interaction in a feedback loop and became one of the most well-recognized approaches for evaluating diabetes." (PMID 21152006, 2010). "Diabetes mellitus is a group of complex multisystem metabolic disorders characterized by a relative or absolute insufficiency of insulin secretion and or concomitant resistance to the metabolic action of insulin on target tissues." (PMID 20922079, 2010). "Diabetes is a chronic disease that occurs when pancreatic islets fail to produce sufficient insulin and/or the sensitivity of glucose-metabolizing tissues to insulin decreases." (PMID 21113299, 2010). "Immunohistochemical analysis of insulin-positive cells in pancreatic sections also proved more effective de-ATSCs treatment of diabetes compare to control ATSCs, since mass of insulin-producing cells became comparable to that of healthy controls." (PMID 20161735, 2010). "While STZ-induced diabetes elevated all the experimental parameters examined and lowered the insulin output, a pretreatment with 3-AB, NIC or TAU reversed these trends to a significant extent." (PMID 20804590, 2010). "The surprising capacity of the mature liver to serve as a potential source of tissue for generating functional insulin-producing cells provides a potential strategy for the treatment of diabetes." (PMID 20195523, 2010). "In cerebral cortex curcumin and insulin treatment reversed the altered expression in diabetes to near control." (PMID 20513244, 2010). "Further investigation of the effect of C. longa on glucose and insulin levels in patients with type 2 diabetes mellitus is needed." (PMID 20937162, 2010). "Type 2 diabetes mellitus (T2DM) is a progressive disease in which increasingly poor insulin sensitivity and hyperinsulinemia precede, typically for several years, the onset of frank diabetes." (PMID 21170321, 2010). "Patients who were switched to insulin therapy were significantly older, had a significantly longer diabetes duration, and had more diabetes complications than patients who remained on an oral diabetes regimen." (PMID 20920319, 2010). "The first case was a 35-year-old male who presented with insulin-treated diabetes, obesity, hypertension, polydactyly, normal cognitive functions, an ataxic gait, blindness secondary to RP, dyslipidemia, impaired renal function, and multiple renal cysts." (PMID 20103962, 2010). "Several lines of evidence also revealed that viral-vector mediated ectopic expression of pancreatic transcription and differentiation factors can induce liver cells to express insulin and cure diabetes in mice." (PMID 20195523, 2010). "34-year-old Kuwaiti male was referred to our diabetes clinic for insulin-treated diabetes and uncontrolled hyperglycemia." (PMID 20103962, 2010). "His diabetes was gradually controlled with increasing doses of insulin and metformin given at doses of up to 2 g per day along with statins." (PMID 20103962, 2010).
diabetes (continued). "The average state prevalence of diabetes was 5.5%; 30% of the people with diabetes used insulin; the mean time since detection of diabetes was 8.8 years." (PMID 20492699, 2010). "A far higher proportion of people with diabetes were receiving treatment (68%), which included insulin (n = 32), tablets (n = 143) and/or diet control (n = 43)." (PMID 20860807, 2010). "As treatment for their diabetes, 12 subjects took oral agents, 2 took insulin, and 2 were on insulin and an oral agent." (PMID 20822968, 2010). "Angiotensin II (Ang II) plays a major role in the pathogenesis of insulin resistance and diabetes by inhibiting insulin's metabolic and potentiating its trophic effects." (PMID 20383279, 2010). "Two hours after a glucose load of 1.75 g/kg blood glucose level was 258 mg/dL, HbA1c 6.8% and insulin level was 642.9 mIU/mL, revealing a state of insulin resistance and type 2 diabetes mellitus (DM)." (PMID 21274335, 2010). "The insulin therapy was an inhaled insulin and expectations, experiences and diabetes treatment satisfaction were assessed using three validated questionnaires: EAITQ, EWITQ and DTSQ, respectively." (PMID 20370840, 2010). "Diabetes mellitus is a chronic metabolic disorder characterized by abnormally high urine and blood glucose levels (i.e., hyperglycemia) due to insufficient insulin levels." (PMID 23554650, 2010). "On admission, patients with insulin-treated diabetes were older, sicker, as reflected by higher simplified acute physiology system II (SAPS II) and SOFA scores, and more likely to be receiving hemodialysis than the other patients." (PMID 20132545, 2010). "This was tested in trials where MI patients with diabetes where treated intensively with insulin to better glycemic status." (PMID 20525192, 2010). "Diabetes mellitus extensively alters lipid metabolism and, in turn, dyslipidemia appears to play an integral role in the development of impaired insulin secretion." (PMID 20236525, 2010). "Antenatal steroids for fetal lung maturation are not contraindicated but should be administered with additional insulin in women with insulin treated diabetes (D)." (PMID 20416099, 2010). "A role of PARP activation in pancreatic islet cell damage by STZ can be ascertained from the circulating levels of both insulin and glucose, with the type of diabetes being a determined by the dose of STZ administered." (PMID 20804590, 2010). "Two hours after glucose loading, the glucose tolerance test revealed a glucose level of 258 mg/dL, a HbA1c value of 6.8%, and an insulin level of 642.9 mIU/mL, documenting a state of insulin resistance and type 2 diabetes mellitus." (PMID 21274335, 2010). "As expected, alloxan induced-diabetes resulted in decreased blood insulin in both sedentary and trained rats." (PMID 20431804, 2010). "Previous studies in other countries have shown that polymorphisms from the insulin – IGF2 region can predispose to some complex pathological traits, particularly those involving diabetes." (PMID 21637566, 2010). "Overall, our study presents a new avenue for altering the course of diabetes progression as there has been limited success in obviating the need for parenteral insulin-replacement therapy of T1D to date." (PMID 20949090, 2010). "In our previous studies; we have shown that insulin levels in plasma were significantly decreased, whereas glucose levels in plasma were significantly increased during the development of diabetes (all P < 0.05)." (PMID 20735837, 2010). "The impaired GLP-1 secretion in people with diabetes results in defective glucose-stimulated insulin secretion, reduced glucose clearance and, often, quicker gastric emptying." (PMID 27713366, 2010). "Type 1 diabetes mellitus (T1DM) is a multifactorial autoimmune disease in which the insulin producing β cell population is destroyed by the infiltrated T lymphocytes." (PMID 20350307, 2010).
diabetes (continued). "Two other family members who carried the INS R6H were diagnosed with diabetes when 51 years old and with GDM when 27 years old, respectively." (PMID 20226046, 2010). "Alginate is a bio-inert material used in a variety of biomedical applications including encapsulation of insulin producing islets for diabetes therapy, wound healing, implants for cardiac remodeling following infarction." (PMID 20386609, 2010). "We reported a case of a 23-year-old black female with an 11 year history of type 1 diabetes, regularly monitored in the department of diabetes, in use of 0,98 UI/kg/day of human insulin, which presented an allergic reaction 24 h after ramipril use." (PMID 20180980, 2010). "An Arabic 48-year-old man from North Africa (Tunisia) with a ten year history of diabetes mellitus is treated by insulin twice a day for seven years." (PMID 20205769, 2010). "We observed that OX1R co-localizes with INS in pancreatic beta cell and it is up-regulated in diabetes." (PMID 20062799, 2010). "The number of OX1R-containing cells that contain INS decreased significantly (p<0.001) after the onset of diabetes." (PMID 20062799, 2010). "In the present study we showed the effects of insulin induced hypoglycemia and streptozotocin induced diabetes on the cerebellar cholinergic receptors, GLUT3 and muscle cholinergic activity." (PMID 20137086, 2010). "Both islet transplantation and insulin treatment were effective at preventing hypergylcemia and recurrence of diabetes, with blood glucose control by islet transplantation superior to insulin implants (139.4±7.5 and 181.6±8.3 mg/dl respectively, P<0.05)." (PMID 20090914, 2010). "Of the 3147 patients included in the SOAP study, 226 (7.2%) had a prior diagnosis of insulin-treated diabetes mellitus." (PMID 20132545, 2010). "Insulin is a 51 amino acid (aa) polypeptide hormone essential for normal glucose homeostasis and is therefore useful in treating diabetes." (PMID 20462406, 2010). "In our model of streptozotocin-induced diabetes, beta cells and insulin levels are decreased; thus, inhibition of rho kinase cannot improve insulin signaling." (PMID 20368772, 2010). "Insulin appears to be important in regulating the utilization of ketone bodies, and the uptake of β-hydroxybutyrate and acetate by sheep hind limbs is impaired during alloxan diabetes and is restored by insulin." (PMID 20613964, 2010). "The proband was diagnosed at 13 years of age and had been treated with insulin since onset of diabetes." (PMID 20226046, 2010). "At the start of the study, there were 156 (2.34%) patients with diabetes treated with diet, 372 (5.58%) with diabetes treated with oral medication, and 140 (2.10%) with patients with diabetes treated with insulin." (PMID 20525192, 2010). "Diabetes mellitus (DM) is characterized by disarrangement of the metabolism of carbohydrates, proteins and lipids caused by the complete or relative insufficiency of insulin secretion and/or insulin action." (PMID 20416073, 2010). "The cost of hypoglycaemic agents for treating diabetes was €49.6 million (17% of total costs) of which €35.1 million (70%) represented insulin and analogues (A10A) and the rest oral glucose lowering drugs (A10B)." (PMID 20854689, 2010). "Successive reduction of insulin from the pancreatic β-cells in patients with type 2 diabetes mellitus is considered to be a major factor for this attenuation of the drug effects." (PMID 21070671, 2010). "We have explored management of childhood diabetes and focused on blood glucose monitoring and insulin management as a key exemplar concerning medicine management, self-care and concordance." (PMID 20875112, 2010). "Previous studies on the influence of insulin therapy on BC of patients with diabetes mellitus have been limited because the methods for analyzing BC (tritiated water, underwater weighing or four-compartment model) are difficult to use in clinical practice." (PMID 20721344, 2010).
diabetes (continued). "The CAMBoD project was also influential in reducing the prices of insulin and diabetes related products such as testing kits in across the country." (PMID 20403170, 2010). "Type 2 diabetes mellitus is a complex disease, which is characterized by abnormal hepatic glucose output, insulin resistance and impaired insulin production." (PMID 21085649, 2010). "Chronic leucine supplementation lowers HbA1c level and improves glucose and insulin homeostasis in multiple mouse models of obesity and diabetes." (PMID 20624298, 2010). "The facts' that increased blood glucose level and decreased body weight, observed during diabetes, are similar with previous reports as a result of the marked destruction of insulin secreting pancreatic β-cells by STZ." (PMID 20513244, 2010). "Insulin-producing pancreatic islet β cells (β-cells) are destroyed, severely depleted or functionally impaired in diabetes." (PMID 20084282, 2010). "Random glucose commonly rises to 300-500 mg/dl, often over 600 mg/dl, in Nile rats with advanced diabetes and insulin depletion, whereas fasting glucose seldom exceeds 400 mg/dl, even in the worst case of diabetes." (PMID 20398338, 2010). "Insulin is possibly diffused into the pleural cavity according to bloodstream levels following diabetes treatment." (PMID 20814548, 2010). "The majority of cross-sectional studies asked about the type of diabetes when assessing prevalent diabetes or excluded participants using insulin within the first year of diagnosis." (PMID 20976133, 2010). "A computational model of insulin secretion and glucose metabolism for assisting the diagnosis of diabetes mellitus in clinical research is introduced." (PMID 23554650, 2010). "Insulin delivery options for patients with diabetes continue to expand with the development of new systems that aim to be straightforward, inconspicuous and less painful." (PMID 20370840, 2010). "Current diabetes treatment paradigms encourage aggressive insulin regimens to manage blood glucose levels within normal ranges and prevent increases in HbA1c." (PMID 20418955, 2010). "Further investigation of the role of insulin in the TRAIL expression in diabetes was done with VSMCs in vitro." (PMID 20634940, 2010). "In our study cohort 21/66 (31.8%) patients suffered from diabetes mellitus and were treated with oral antidiabetic medication 15/66 (22.7%) or insulin 6/66 (9.1%)." (PMID 20624277, 2010). "The psychological changes observed in diabetes appear to persist even when the diabetic state is well-controlled with insulin administration." (PMID 20868513, 2010). "Longitudinal data in older persons with IGT also indicate that the proinsulin-to-insulin ratio is a marker for progression to diabetes." (PMID 21162746, 2010). "Several epidemiological and experimental studies have demonstrated that impaired insulin and insulin signaling transduction occur in both diabetes mellitus and AD, suggesting a linkage between these two disorders." (PMID 21044348, 2010). "At baseline, mean total insulin levels were significantly greater for patients with diabetes, compared to controls (p < 0.001)." (PMID 20573241, 2010). "Oxidative stress is increased in diabetes with leptin administration reportedly improving insulin sensitivity in normal and diabetic rodents." (PMID 20671928, 2010). "It was observed from the earlier studies that administration of pyridoxine along with insulin serves as a control measure for diabetes, regulating GDH activity and glucose level." (PMID 20868513, 2010). "So, H2S can be a good target to treat diabetes but further detail investigation of role of H2S in insulin resistance is require to study." (PMID 21264117, 2010). "Type 1 diabetes accounting for about 5-10% of all diabetics is an end stage insulitis characterized by the presence of only 10-20% of insulin producing β-cells." (PMID 20350307, 2010).
diabetes (continued). "It thus seems promising that inhibition of PDEs other than PDE3 potentiates an effect of insulin secretion and can therefore be more advantageous for the treatment of diabetes." (PMID 21152070, 2010). "This was a planned substudy from the European observational Sepsis Occurrence in Acutely ill Patients (SOAP) study to investigate the possible impact of insulin-treated diabetes on morbidity and mortality in ICU patients." (PMID 20132545, 2010). "In this work we will review the results obtained by different investigators about the relation between ghrelin and glucose metabolism and insulin release as well as its possible therapeutic role in disease states like diabetes." (PMID 20700401, 2010). "The finding implicates a promising role of early administration of insulin-sensitizing therapy in prolonging survival of breast cancer patients with type 2 diabetes mellitus." (PMID 24281091, 2010). "The Diabetes Control and Complications Trial (DCCT) led to considerable improvements in the management of type 1 diabetes, with the wider adoption of intensive insulin therapy to reduce the risk of complications." (PMID 20456170, 2010). "Overall, 28 insulin-naive type 2 diabetes subjects (mean ± SD age, 61.5 ± 6.7 years; diabetes duration, 9.8 ± 6.5 years; HbA1c, 7.1 ± 0.5%; BMI, 30.7 ± 4.3 kg/m2) treated with metformin and sulfonylurea were randomized to add once-daily GLA or NPH at bedtime." (PMID 20415692, 2010). "Obese mice with diabetes showed a significant improvement in glycemic control and insulin sensitivity when treated with 3% dietary curcumin for five weeks." (PMID 20937162, 2010). "These odds ratios were slightly attenuated after adjustment for age, and then additionally after separate adjustment for, glucose, insulin, physical activity, smoking, alcohol intake, diabetes in the family, and hypertension." (PMID 20529259, 2010). "Marked elevations in fasting glusose and plasma lipids in the early-onset group at study end indicated that their diabetes was, indeed, more advanced, and that they had proceeded to stage D where the plasma insulin was depleted as result of beta-cell failure." (PMID 20398338, 2010). "Recent data have, however, highlighted factors that predispose to hypoglycaemia such as continuous haemofiltration, diabetes, mechanical ventilation, sepsis, administration of insulin and inotropic drugs, and brain lesions." (PMID 20840773, 2010). "Stage C (entrenched diabetes) was characterized by both elevated insulin (>3.5 ng/ml) and random blood glucose (>150 mg/dl); Stage D represented depressed insulin, while blood glucose and lipids were still elevated (beta-cell failure)." (PMID 20398338, 2010). "More research is required to understand the role of diabetes, insulin, and hyperglycemia in critically ill patients with ALI." (PMID 20716368, 2010). "Patients on insulin therapy have the possibility to register in the hospital where they receive care from a multidisciplinary team (diabetologist, diabetes educator, dietician)." (PMID 20630062, 2010). "Diabetes reduced blood insulin, liver glycogen stores and increased blood glucose and neutrophil count." (PMID 20431804, 2010). "In people with type 2 diabetes (the most common type of diabetes), blood sugar control fails because the fat and muscle cells that usually respond to insulin by removing sugar from the blood become less responsive to insulin (insulin resistant)." (PMID 20421924, 2010). "We describe a 3-year-old girl with permanent neonatal diabetes mellitus with a mutation in the KCNJ11 gene (R201H), who was successfully transferred from subcutaneous insulin to oral glibenclamide, with a marked improvement in glycemic control." (PMID 20220270, 2010). "No other significant association between the alleles or genotypes of insulin -23Hph and IGF2 Apa and diabetes or obesity was identified." (PMID 21637566, 2010).